ALYREF (Aly/REF export factor)
Diseases named in the same sentence as ALYREF in open-access papers (continued):
Sharing a sentence is not in itself a finding about the gene and the disease.
cancer (continued). "Finally, we evaluated ALYREF expression as well as its prognostic values in pan-cancer." (PMID 41326692, 2026). "Patients with overexpressed ALYREF in these cancers might also benefit from immunotherapy." (PMID 38361753, 2024). "Taking into consideration the aberrant expression and prognostic value of ALYREF and YBX1 across cancers, we selected KIRP, LGG and LIHC as the main cancer types for further investigation." (PMID 38238581, 2024). "Initially, the expression levels of ALYREF and YBX1 were collected in 33 different types of cancers from the TCGA and GTEx databases." (PMID 38238581, 2024). "It was showed that ALYREF has more total amplification (including homozygous CNV and heterozygous CNV) in various cancers." (PMID 38491127, 2024). "ALYREF and YBX1 as members of m5C readers that have garnered increasing attention in cancer research." (PMID 38238581, 2024). "We chose the three cancer types with the greatest significance level, ACC, KIPAN, and LIHC and studied the correlation between ALYREF gene expression and cancer stages." (PMID 38491127, 2024). "These resources provide valuable insights into the molecular mechanisms and clinical diagnosis of ALYREF and YBX1, thus contributing to a more comprehensive understanding of m5C readers in cancer biology." (PMID 38238581, 2024). "The forest plot analysis of overall survival (OS) revealed a significant correlation between the expression of ALYREF, YBX1 and prognostic value across various cancers." (PMID 38238581, 2024). "By thoroughly analyzing ALYREF and YBX1, we aim to provide a solid basis for the identification of novel biomarkers for the early diagnosis of cancer and the prognosis of therapy." (PMID 38238581, 2024). "We showed in this study that LINC02159 upregulated YAP1 expression by stabilizing its mRNA through ALYREF-mediated m5C modification, which represents a new mechanism for the regulation of YAP1 in cancer." (PMID 37537569, 2023). "As ALYREF has been previously proposed as an RNA-binding protein and the long noncoding RNA NEAT1 has been involved in the growth and cancer stemness of TNBC, we decided to further decipher a possible link between these two molecules." (PMID 35776213, 2022). "In a pan-cancer tissue analysis that included HCC, we assessed the expression of ALYREF compared to normal tissues using The Cancer Genome Atlas database." (PMID 34367948, 2021). "Depletion of ALYREF results in the reduced metastatic capacity of human oral squamous cell carcinoma cell lines, demonstrating the increased TREX dependence in cancer cells." (PMID 27679854, 2016). "hnRNPA2B1 selectively facilitates the nuclear export of m6A-modified mRNAs by interacting with the Aly/REF export factor (ALYREF)-nuclear RNA export factor 1 (NXF1) complex, thereby enhancing the expression of stemness-related genes critical for cancer stem cell maintenance." (PMID 40986143, 2025). "The positive pan-cancer correlations with m1A RNA methylation regulatory proteins YTHDF2 and ALKBH1, m5C methylation regulatory proteins DNMT1, DNMT3B, and ALYREF, and m6C RNA methylation regulatory proteins HNRNPC, HNRNPA2B1, and ELAVL1 were particularly significant." (PMID 36090896, 2022). "For ALYREF, researches related to the function and mechanism of ALYREF in human cancers remain absent." (PMID 35812757, 2022). "Previous studies showed the Aly/REF export factor (ALYREF) and Y-box binding protein 1 (YBX1) may act as significant readers for m5C, taking part in cancer-related biological processes." (PMID 34926580, 2021). "ALYREF directly interacts with RRP1B, so the increased expression of ALYREF in cancer cells may titrate away RRP1B allowing metastasis to develop uninterrupted." (PMID 27679854, 2016).
cancer (continued). "These collective findings establish the dual role of FASN in suppressing apoptosis and promoting angiogenesis across multiple cancer types, thereby substantiating our hypothesis that FASN acts as the mechanistic executor through which the circHIPK3/ALYREF axis drives oncogenic effects in GBC." (PMID 40466438, 2025). "Despite considerable analysis carried out in this study on the ALYREF and MYCN regulatory circuit, it is not yet fully clear how MYCN-promoted oncogenic levels of ALYREF reprogram cells to help the cancer state." (PMID 33767157, 2021).
ALYREF also shares sentences with these, for which no sentence is quoted: infection (3 papers); esophageal cancer (2); hematologic malignancies (2); amyotrophic lateral sclerosis (1); cardiovascular disorder (1); cerebrovascular accident (1); cholangiocarcinoma (1); colorectal cancer (1); coronary stenosis (1); diffuse large B-cell lymphoma (1); esophageal squamous cell carcinoma (1); head and neck squamous cell carcinoma (1); Herpes simplex infection (1); influenza (1); lung squamous cell carcinoma (1); lymph node metastasis (1); lymphoid neoplasm (1); malaria (1); medulloblastoma (1); mesothelioma (1); neuropathic pain (1); pan (1); pheochromocytoma (1); pheochromocytoma and paraganglioma (1); serous ovarian cancer (1); squamous cell carcinoma (1); stomach cancers (1); tauopathy (1); testicular cancer (1); Thyroid carcinoma (1).
A further 5 diseases each share a sentence with ALYREF in 1 paper.